IL10 (interleukin 10)
Diseases named in the same sentence as IL10 in open-access papers (continued):
Sharing a sentence is not in itself a finding about the gene and the disease.
depression (continued). "Both BDNF and IL-10 levels exhibited strong inverse correlations with Hamilton Depression Rating Scale (HAM-D) scores (BDNF: ρ = −0.61, p < 0.001; IL-10: ρ = −0.52), reinforcing their protective roles in mitigating depressive symptoms." (PMID 40823578, 2025). "A recent study has revealed that the intranasal delivery of the anti‐inflammatory molecule IL‐10 can significantly enhance cognitive function in mice exhibiting depression‐like behaviors." (PMID 40237247, 2025). "Meta-analysis showed that IL-10 was higher in the test group compared with the control group (SMD: 0.77, 95% CI:0.26, 1.28), indicating that depression animals treated with acupuncture had significantly higher levels of IL-10 (P < 0.05)." (PMID 41244868, 2025). "Recent investigations have revealed that the intranasal administration of interleukin 10 (IL‐10) has the potential to alleviate depressive behavior and cognitive function in mouse models of depression." (PMID 40237247, 2025). "In contrast, level of IL-10 particularly in serum is generally increased with depression, which was also consistent with our findings." (PMID 40179065, 2025). "qPCR results showed that knockdown of Homer1 improved the expression of inflammation‐related markers IL‐1β, TNF‐α, IL‐10, and depression‐related markers ERCCL2, SLC6A4, and GAD1 in primary neurons, both in the PTSD group and in the TBI+Hcort group." (PMID 39665190, 2025). "In parallel, interleukin-10 (IL-10), a key anti-inflammatory cytokine, was also significantly decreased in the depression group." (PMID 40823578, 2025). "Instead, depression showed a different neuroinflammatory response with lower IL-1β and higher IL-6 and IL-10 expression compared to the controls." (PMID 40179065, 2025). "In the depression group, increase of IL-6 and IL-10, and decrease of IL-1β were observed compared to controls, with no changes detected for the other cytokines and the endothelial markers." (PMID 40179065, 2025). "Our findings indicate that acupuncture can reduce TNF-α and IL-1β levels while increasing IL-10 and IL-4 levels in depression animals." (PMID 41244868, 2025). "Low level of IL-10 in plasma were associated with poor prognosis in AIS and increased risk of post-stroke depression, but high levels of IL-10 are also risk factors for early neurological deterioration in AIS." (PMID 38817358, 2024). "The presence or absence of suicidal behavior was used as the status variable in patients with depression, and IL-10 was employed as the test variable for the ROC curve analysis." (PMID 39882160, 2024). "Although most studies on the “cytokine theory of depression” are centered on increased levels of proinflammatory cytokines, the role of anti-inflammatory IL-10, one of the most important anti-inflammatory cytokines, was investigated in depression." (PMID 38731995, 2024). "Polymorphisms in genes such as IL-1β, IL-6, IL-10, TNF, MCP1/CCL2, CRP, and phospholipase A2 are among the most consistently observed findings in major depressive disorder." (PMID 39723161, 2024). "Unique combinations of plant extracts decreased serum IL-10 compared to the stress group; however, the effects on depression-like behaviors need to be analyzed." (PMID 38791125, 2024). "Further, depression-like behavior, cognitive deficits, and enhanced neuroinflammation in IL-10 KO mice improved upon pretreatment with IL-10." (PMID 38739942, 2024). "Our study indicates that the inhibition of PPARγ leads to a suppression of IL-10 expression in microglia during depression." (PMID 38822367, 2024). "Animal models of depression have confirmed that high concentrations of pro-inflammatory cytokines and low concentrations of anti-inflammatory mediators like IL-10 and IL-4 in the brain correlate with the progression of depression." (PMID 39130643, 2024). "Conversely, interleukins like interleukin-10 (IL-10) and interleukin-4 (IL-4) have distinct but interconnected roles in immune system regulation and its relationship with depression." (PMID 39335507, 2024).
depression (continued). "Elevated plasma IL-2 at 24 h was associated with more severe post-concussive symptoms, while elevated IL-10 at 6 months correlated with greater depression and PTSD symptoms." (PMID 38397895, 2024). "For example, studies included in a meta-analysis found an association between increased levels of IL-1RA, IL-6, IL-10, IL-12, sIL-2R, sIL-6R, and TNF-α, and decreased levels of IFN-γ and IL-4, in adult patients with depression." (PMID 38474387, 2024). "Previously, IL-10 has been widely studied in the pathogenesis of depression, although the relationship between it and depression is unclear, and many studies even present opposite conclusions." (PMID 39882160, 2024). "This also explains the increase in 5-HT content, decrease in pro-inflammatory factors TNF-α and IL-6 content, and increase in anti-inflammatory factor IL-10 content in the serum of mice with depression-like behavior after oral administration of asiaticoside." (PMID 39494347, 2024). "The aim of our study was to investigate the role of pro-inflammatory IL-6, TNF-α, and IL-1β and anti-inflammatory IL-10 and TGF-β in depressive disorders observed in patients suffering from pain caused by disk herniation (DH) qualified for surgery." (PMID 38646609, 2024). "For instance, preclinical studies have demonstrated positive results regarding central IFNγ and NGF for depression, as well as peripheral IL-10 for mania." (PMID 37240605, 2023). "Patients with depression were also found to have lower IL-10 levels and an increased IL-6/IL-10 ratio in comparison with healthy individuals, which suggests disturbances in the regulation of cytokine secretion in depression." (PMID 37840785, 2023). "Regarding anti-inflammatory cytokines IL-4 and IL-10 were unchanged between depression patients and controls." (PMID 37575572, 2023). "IL-1, TNFα, IFNγ, NGF, or microglia activation in depression, as well as IL-4, TNFα, and IL-10 in mania, were normalized by celecoxib in preclinical studies." (PMID 37240605, 2023). "Compared with healthy controls, the levels of interleukin-4, interleukin-6, and interleukin-10 changed significantly in major depressive disorder patients." (PMID 37275977, 2023). "Supporting this, increased levels of proinflammatory cytokines including IL-1β and IL-6 and decreased levels of anti-inflammatory cytokines including IL-4 and IL-10 have been detected in people living with depression." (PMID 38053532, 2023). "At 24 h, elevated IL-2 (p = 0.001) and lower IL-6 (p = 0.035) and IL-17a levels (p = 0.007) ass. with severe PCS at 1 week (p = 0.001).At 6 months, elevated IL-10 ass. with depression (p = 0.004) and PTSD (p = 0.001)." (PMID 37251220, 2023). "Increased levels of cytokines such as IL-6, IL-10, IL-12, IL-13, and IL-17 were found in individuals with depression." (PMID 37240864, 2023). "As secondary goals, the use of analgesic medication, quality of life, depressive symptoms, and possible correlations between plasma levels of interleukin (IL)-1 beta, IL-6, and IL-10 as predictors of pain and depression were evaluated." (PMID 36944694, 2023). "Conversely, the role of anti-inflammatory cytokines in depression, such as one of the most important, IL-10, is also under investigation." (PMID 37680396, 2023). "It is proposed that IL‐10 is an anti‐inflammatory, immunomodulatory cytokine that is shown to improve neurological injuries like ST and depression and acts against excitotoxicity through the inhibition of TNF‐α synthesis." (PMID 36655100, 2023). "Studies demonstrate that IL-10, assayed in the blood, can be a peripheral predictive marker of postpartum depression symptoms." (PMID 37892657, 2023). "The most common cytokines associated with poor psychological outcomes involving PTSD and/or depression in the chronic mTBI population were IL-6, TNFα, IL-10, and CRP." (PMID 35053845, 2022).
depression (continued). "In depression, IL-10 is one important component of the “compensatory immune-regulatory system” (CIRS) which tends to down-regulate the primary immune–inflammatory response." (PMID 35330475, 2022). "The biomarkers assessed in the studies involving depression include IL-6 (n = 5), IL-10 (n = 4), TNF-α (n = 4), IL-1β (n = 2), CRP (n = 2), and IL-7 (n = 1)." (PMID 35053845, 2022). "It is noteworthy that IL-1β, IL-6, and IL-10 are the most frequently reported cytokines in depression and affective disorders." (PMID 36387880, 2022). "Previous studies have reported reduced IL-10 in patients with depression and pain, respectively, but our study is the first to report reduced IL-10 in depression and pain comorbidity models." (PMID 35733107, 2022). "The results showed that the levels of NPY, T, IL-10, and IL-4 in the normal group, depression group, and DCMI group were from high to low." (PMID 35432561, 2022). "The immune effects of IL-1β, IL-4, IL-10 and IL-8 in depression or PTSD have also been reported by other authors." (PMID 35326343, 2022). "Overall, this review supports the finding that elevated IL-10 levels seen in chronic mTBI patients are associated with PTSD and depression." (PMID 35053845, 2022). "We observed elevated IL-1β, IL-6 and reduced IL-10 in the reserpine-induced hyperalgesia and depression comorbidity model group in our present study." (PMID 35733107, 2022). "IL-10 knockout mice displayed a decreased latency to immobility in a forced swim test as a measure of depression, which was rescued by the administration of IL-10 that is known to inhibit pro-inflammatory cytokine production." (PMID 35546876, 2022). "One suggested explanation for this discrepancy is that IL-10 levels increase initially in response to acute inflammation connected with depression as a part of the compensatory immune system." (PMID 36614020, 2022). "Studies have shown that administration of IL-10 can rescue depression-related learning and memory defects and restore the density of hippocampal dendritic spines." (PMID 35733802, 2022). "Recently, the role of anti-inflammatory cytokines in attenuating the effect of inflammatory mediators (i.e., IL-10, IL-4, and IL-1ra) has also been taken into account in depression studies." (PMID 35886944, 2022). "There was also a significant relationship between upregulated IL-10 levels and PTSD (B = 0.8, t = 2.60, p < 0.01), and a weak relationship between IL-10 levels and depression (B = 0.421, t = 1.41, p = 0.063) within mTBI populations." (PMID 35053845, 2022). "Clinical and animal research revealed that increased IL-6 and decreased IL-10 would result in depression." (PMID 35757220, 2022). "The levels of neuropeptide Y (NPY), testosterone (T), and IL-1β, IL-6, TNF-α, IL-10, and IL-4 in the peripheral blood plasma of normal people, patients with depression, and patients with DCMI were measured." (PMID 35432561, 2022). "In contrast, within the All Low class, depression scores were positively correlated with soluble IL-10 (r = 0.53, p = 0.035, n = 17) and sleep disturbances scores negatively correlated with soluble IFN-γ (r = −0.33, p = 0.042, n = 40)." (PMID 35547250, 2022). "The study assessed the concentration of IL-1β, IL-4, IL-8 and IL-10 in depression alone and with PTSD." (PMID 35326343, 2022). "Only a few studies investigated a priori chosen proteins, such as sICAM-1, IL-10, CRP, and reported associations with NPS in general as well as with apathy and depression." (PMID 35326481, 2022). "After 3 weeks of abstinence, however, IL-10 was found negatively relating to depression, anxiety and craving." (PMID 34869080, 2021). "In conjunction with measures of pregnancy-specific anxiety and depression, serum biomarkers (IL-2, IL-6, IL-10, IL1-B, TNF-α, CRH, CRP, and cortisol) were analyzed for each trimester throughout pregnancy." (PMID 34360332, 2021).
depression (continued). "Patients with depression showed increased levels of IL-8, IL-10, IL-12, and IL-13, whereas IL-6 and TNF-α showed mixed results between studies." (PMID 33578686, 2021). "Il10–/– mice have more depression and helplessness-like behavior in forced-swim tests; this can be normalized by injection of IL-10." (PMID 33717157, 2021). "In contrast, anti-inflammatory IL-10 was reduced in the cortex and hippocampus of rats subjected to chronic bondage stress, and depression-like behavior was reversed by administration of recombinant IL-10." (PMID 34531719, 2021). "Recent evidence has suggested a potential role for IL-10 toward the homeostasis in animal models of depression, secondary to inflammation." (PMID 34040126, 2021). "The most commonly involved inflammatory markers observed in the pathogenesis of both depression and Psoriasis are IL-6, IL-17, IL-13, IL-23, IL-10, IL-1β, and type A cytokines (TNF-α, IL-2, INF-γ) through Th1 and Th17 lymphocytes mediated processes." (PMID 34183985, 2021). "A study examining 66 patients undergoing hematopoietic stem cell transplantation showed that those with depression had a higher ratio of IL-6/IL-10 than controls." (PMID 33810574, 2021). "In the present study, many anti-depressant targets of EMO against depression were associated with the inflammatory response such as IL6, TNF, IL10, CRP, IL1B, CTLA4, ALB and IL2." (PMID 34051074, 2021). "Adding mother’s depression scores to the model had an additive effect on this decrease in cytokine concentrations in relation to IL-10." (PMID 34064967, 2021). "Conversely, changes in self-reported sleep problems were related to an increase in depression and anxiety (p = 0.001 and p = 0.01 respectively), the T helper 2 (Th2) cytokine IL-5 (p = 0.027), and the counter-regulatory cytokine IL-10 (0.016)." (PMID 33598780, 2021). "A host’s infection is characterized by elevated levels of IL-10, which can reduce depression via its immunosuppressive and anti-inflammatory activities." (PMID 34451515, 2021). "Studies have shown a correlation between microglial expression of β‐endorphin and IL‐10 or endomorphin‐2 in depressive disorders and chronic pain." (PMID 34111331, 2021). "Altered IL-6 expression alone cannot account for depressive symptom, but clinical and animal studies showed that increased IL-6 and decreased IL-10 will lead to depression." (PMID 32611425, 2020). "Multiple therapeutic targets were mediated by active ingredients of XYS, such as IL2, IL4, IL6, IL10, and STAT3, which are involved in immune and inflammatory responses closely associated with depression." (PMID 32256358, 2020). "A study has evaluated the relationship between depression and IL-6 and IL-10 in patients undergoing hematopoietic stem cell transplantation." (PMID 32235786, 2020). "Lower IL-10 has been observed in depression, while IL-10 was elevated after antidepressant treatment." (PMID 32714875, 2020). "Based on the univariate analysis of the GLM, we found significant differences in the years of education, cytokines (IL-1β, IL-2, IL-6, IL-12p70, IL-17A, IFNγ, TNFα, IL-10, and IL-13), and depression severity (indicated by the PHQ) among the groups." (PMID 32703187, 2020). "High IFNγ and IL10 also predicted better HADS “depression” outcome, albeit with lower R2 than TNFα in the confounder controlled model (not shown)." (PMID 33240126, 2020). "First, we found that the baseline levels of IL-10, IL-12p70, IL-13, IL-17A, IL-1β, IL-2, IL-23, IL-5, IL-6, IL-7, and MIP-1β were associated with depression symptoms." (PMID 32699226, 2020). "Both TNF-α and IL-10 were previously reported to be associated with depression, in which TNF-α is a pro-inflammatory cytokine, while IL-10 is an anti-inflammatory cytokine." (PMID 31881712, 2019). "In the paroxetine study, at randomisation we observed a positive correlation between IL-6 (r = 0.23, p = 0.018) and IL-10 (r = 0.19, p = 0.045) levels and severity of depression evaluated by HAMD." (PMID 31375659, 2019).
depression (continued). "It is important to note that IL-10, in addition to its anti-inflammatory immune function, has effects on the brain and behavior, taking part in the modulation of mood, anxiety and depression symptoms." (PMID 31624297, 2019). "In both control groups, IL10 levels positively correlated with fewer depression symptoms according to Hamilton-D." (PMID 31956305, 2019). "We measured the level of IL-10 in the serum samples of our patients in depression and remission and saw higher, compared with samples from healthy people, concentrations of IL-10 in euthymic patients." (PMID 30971748, 2019). "The concentration of cytokines (IL-6, TNF-α, IL-17A, IL-10) was measured in the serum of healthy subjects and BD patients in remission or depression." (PMID 30971748, 2019). "An interesting study demonstrated positive correlations between Th1 (IL-6) and Th2 (IL-10) cytokines with depression, anxiety, and perceived stress in women during mid-pregnancy [14–28 gestation weeks (gwks)]." (PMID 30943938, 2019). "We found that the levels of anti-inflammatory cytokines, such as IL-10, increased in the patients with depression." (PMID 29856741, 2018). "Similar studies have also found increased levels of serum IL-10 in patients with depression, which were decreased or unchanged after antidepressant treatment." (PMID 29856741, 2018). "The presence of chronic inflammation and imbalance in inflammatory cytokines such as IL-6 and IL-10 will influence nervous system neuroplasticity to induce behavioral changes, cognitive impairment, and depression." (PMID 30357038, 2018). "In summary, our results suggest that variations in maternal immune system activity during pregnancy (specifically TNF-α:IL-10) have significant sex-dependent effects on the development of major depression in adult offspring." (PMID 27244231, 2016). "We confirmed that the M1 markers (IL-1β, IL-6, TNFα, iNOS, and CCL2) were induced and that the M2 molecules (Ym1, Arg1, IL-4, IL-10, and TGFβ) were impaired in depression." (PMID 27716270, 2016). "Among continuous variables, patients with depression had significantly higher concentrations of IL-6 and IL-6 to IL-10 ratios (P<0.001)." (PMID 25922648, 2015). "Our results showed that there is a relationship between increased IL-6-to-IL-10 ratios with depression in patients undergoing HSCT (P<0.001)." (PMID 25922648, 2015). "Analysis of correlations between HADS scores within inflammatory, anti-inflammatory markers and some variables associated with depression showed that HADS score were significantly correlated with serum concentrations of IL-6 and IL-6 / IL-10 (P<0.001)." (PMID 25922648, 2015). "In other diseases like depression and multiple sclerosis, low IL-10 production was observed which was reported by several other groups." (PMID 26359865, 2015). "In this study we evaluate relation between depression and IL-6 and IL-10 in patients undergoing hematopoietic stem cell transplantation (HSCT)." (PMID 25922648, 2015). "We did not evaluate another key cytokine, IL6, in this study; however, we have previously reported that IL6 and IL10 expression increased in female patients with active medication refractory depression." (PMID 24826212, 2014). "A neuroprotective role for IL-10 in preventing depression-anxiety like behavior has been postulated." (PMID 25002839, 2014). "For example, elevated serum levels of TNF-α, IL-6, and interleukin-10 (IL-10) have been reported during the early stages of bipolar disorder, and CRP appears to be a biomarker of de novo depression risk." (PMID 24782789, 2014). "IL-10 over-expression mice display less anxiety-like behaviors, while IL-10 knock-out rodents display greater anxiety and depression-like behavior (forced-swim test) with these effects more pronounced in females." (PMID 23382717, 2013).